ACVR1B (activin A receptor type 1B)
Diseases named in the same sentence as ACVR1B in open-access papers (continued):
Sharing a sentence is not in itself a finding about the gene and the disease.
atherosclerosis (1 paper, 2022). A disease characterized by the build-up of fatty material and calcium deposition in the arterial wall resulting in partial or complete occlusion of the arterial lumen.
Atrophy (1 paper, 2021). Any weakening or degeneration, especially through lack of use. "Parallel with in vitro results, T-MSC exosomes significantly downregulated ACVR2A and ACVR1B in Bu-Cy mice, possibly explaining how atrophy genes are attenuated by T-MSC exosomes." (PMID 34440938, 2021).
chronic obstructive pulmonary disease (1 paper, 2023). A chronic and progressive lung disorder characterized by the loss of elasticity of the bronchial tree and the air sacs, destruction of the air sacs wall, thickening of the bronchial wall, and mucous accumulation in the bronchial tree. "Another more recent study found possible implication for ACVR1B gene SNPs in chronic obstructive pulmonary disease." (PMID 37020544, 2023).
cytomegalovirus infection (1 paper, 2023). A herpesvirus infection caused by Cytomegalovirus. "For example, during the latency period in human cytomegalovirus infections, miR-UL148D is one of the most expressed micro-RNAs (miRNA) in myeloid cells and directly targets ACVR1B." (PMID 37020544, 2023).
gastrointestinal stromal tumor (1 paper, 2021). "Moreover, let-7e expression negatively correlates with ACVR1B in gastrointestinal stromal tumors (GIST)." (PMID 33901189, 2021).
leukemia (1 paper, 2020). A malignant (clonal) hematologic disorder, involving hematopoietic stem cells and characterized by the presence of primitive or atypical myeloid or lymphoid cells in the bone marrow and the blood. "Acvr1b knockdown results in inhibition of monocyte/macrophage differentiation in leukemia." (PMID 32066878, 2020).
myopia (1 paper, 2026). "Our meta-analysis identified seven novel suggestive loci associated with myopia progression, including FSTL5 on 4q32.2, SMARCA2 on 9p24.3, CCDC3 on 10p13, GALNT6/ACVR1B on 12q13.13, CRY1 on 12q23.3, ULK2 on 17p11.2, and MYL4/EFCAB13-DT on 17q21.32." (PMID 42094695, 2026).
Parkinson disease (1 paper, 2023). A progressive degenerative disorder of the central nervous system characterized by loss of dopamine producing neurons in the substantia nigra and the presence of Lewy bodies in the substantia nigra and locus coeruleus. "MEG3 and ACVR1B were closely related to graft versus host disease, oxidative phosphorylation, Parkinson's disease, proteasome, ribosome, and splicesome." (PMID 37928394, 2023).
pituitary tumor (1 paper, 2024). A benign or malignant neoplasm affecting the pituitary gland. "This was in agreement with earlier research that ACVR1B can restore activin antiproliferative effects in human pituitary tumor cells." (PMID 38658971, 2024).
pleural mesothelioma (1 paper, 2021). A neoplasm that arises from the mesothelial cells of the pleura. "We collected the methylation profile of pleural mesothelioma, and found 8 novel interactors to be hypomethylated in pleural mesothelioma versus non-tumor pleural tissue, namely, ACVR1B, IL6, MGMT, NRG1, OAT, PHLDA2, PLAUR and TNC." (PMID 33916178, 2021).
small-bowel adenocarcinoma (1 paper, 2020). "In small-bowel adenocarcinoma, exome-wide somatic mutation characterization identified acvr1b and acvr2a as novel candidate driver genes." (PMID 32066878, 2020).
uterine tumors (1 paper, 2023). "ACVR1B and ACVR1C were also mutated in uterine tumors, showing ~34 and 31 mutations each." (PMID 36906706, 2023). "We profiled the data from uterine tumors deposited to the cBioPortal of Cancer Genomics for mutations of the TGFβ signaling pathway and identified several mutations in TGFβ-related receptors (TGFBR1, TGFBR2, ACVR1B, ACVR1C, ACVR2A, ACVR2B) and transcription factors (SMAD2, SMAD3, SMAD4)." (PMID 36906706, 2023).
tumor (51 papers, 2012 to 2025). "Acvr1b encoding the type I activin receptor ALK4 was highly expressed in the clusters of fibroblasts, tumor cells, MonoMacs, DCs, endothelial cells, and pericytes." (PMID 38304252, 2023). "In this case, loss of the ACVR1B mutation can be reconcilable by tumor heterogeneity, or a later selected mutation, or simply a passenger mutation." (PMID 30788462, 2018). "In DSS tumors, activin signaling genes (Acvr1b, Acvr2a, and Smad4) were highly mutated, suggesting the involvement of activin signaling in inflammation-associated tumor development." (PMID 37845228, 2023). "The downregulation of ACVR1B in tumor samples is, at least in part, attributed to epigenetic regulation, particularly DNA methylation, a well-established mechanism for silencing gene expression in cancer." (PMID 41408046, 2025). "Conversely, increased ACVR1B, TNFRSF13B receptor expression correlated with neutrophil and lymphoid infiltrate (correlation: 0.58), associated with TDGF1, TNSF13 tumor ligand expression." (PMID 38077210, 2023). "BMP4, GDF15 and ACVR1B were expressed at higher levels in HER2 positive tumours which were correlated with poorer OS." (PMID 37333824, 2023). "Xenograft node mice model was performed to evaluate the function of acv3UTR on tumor growth in vivo by subcutaneous injection of SGC7901 cells with stable acv3UTR overexpression (lenti-acvr1b) or GFP overexpression (lenti-GFP)." (PMID 32066878, 2020). "Considering the tumor suppressive role of the ACVR1B gene, the development of PC in pancreatic-specific ACVR1B-knockout mice seems reasonable." (PMID 24886203, 2014). "In a xenograft study, ACVR1B-knockdown resulted in a significantly elevated level of tumorigenesis and a larger tumor volume, compared with the control." (PMID 24886203, 2014). "Mice treated with Bu-Cy showed significant increases in activin A receptors, ACVR2A, and ACVR1B, indicating that the state of the tumor microenvironment (such as activin A increase under chemotherapy) could augment activin A responsiveness." (PMID 34440938, 2021). "Results from cancer genome-sequencing studies revealed that the activin A receptor Type 1B (ACVR1B) gene is mutated around 2% of PDAC samples, which may imply that ACVR1B could be a tumor suppressor gene in PDAC." (PMID 31480737, 2019). "Our experimental findings indicate that the activin signal has a tumor suppressive role and that the deletion of the ACVR1B gene may mediate an aggressive cancer phenotype in PC." (PMID 24886203, 2014). "In vivo, ACVR1B-knockdown also enhanced the tumorigenicity and tumor growth." (PMID 24886203, 2014). "To determine whether tumor cell activin receptor signaling is important in enzalutamide resistance in vivo, we generated MycCaP-Bo cells expressing doxycycline-inducible shRNA targeting Acvr1b and Acvr2a, respectively." (PMID 36749798, 2023). "BMP4, GDF15 and ACVR1B were positively correlated with both ER and HER2 in Luminal B (ER+, HER2+) tumours." (PMID 37333824, 2023). "In order to study the role of EGF-CFC family molecules in NB tumor sphere formation, the expression levels of CFC1, TDGF1, ACVR2A, ACVR2B, and ACVR1B were measured using a microarray." (PMID 28620148, 2017). "Activin A inhibited cellular growth in the cell lines with wild-type ACVR1B and SMAD4 genes, and ACVR1B-knockdown enhanced cellular growth and colony formation in vitro as well as tumor growth and tumorigenicity in vivo." (PMID 24886203, 2014). "The repression affects known tumor or metastasis suppressor genes, such as TRIM 29, ACVR1B, and LPAR6, and the sestrins, SESN1 and SESN3; however, in our analyses, ACVR1B, LPAR6, and sestrins were not validated by the qNPA method." (PMID 22276141, 2012). "However, in PDAC alterations of TGFβ signaling through the mutation of genes involved in the pathway (e.g., SMAD4, SMAD3, TβR-I, TβR-II, ACVR1B, and ACVR2A), this role is present in 47% of cases, highlighting that TGFβ can sometimes acts as a tumor promoter." (PMID 32429474, 2020).
tumor (continued). "For other tumor suppressor genes such as MAP2K4, MADH4 (SMAD4/DAC4), ACVR1B (ALK4, activin receptor type 1B) known to undergo germ-line or somatic genetic inactivation in clinically sporadic PC, no germ-line mutations could be identified in any of the FPC kindreds tested." (PMID 24303367, 2013). "Moreover, the 60 s kINPen plasma treatment, which reduced absolute lesion and tumor sizes significantly, was the only treatment not showing a reduction in ACVR1B, ACVR2A, CSF1, EGF, EGFR, IL15, and IL6RA when compared to all other treatments in the high dose DBP group." (PMID 34667240, 2021). "ACVR1B presented negative correlation in both Luminal and TNBC tumours but not in the HER2 positive tumours." (PMID 37333824, 2023).
cancer (41 papers, 2011 to 2025). A tumor composed of atypical neoplastic, often pleomorphic cells that invade other tissues. "Mutation rates and loss of copy number variation for ACVR1B across cancer types ranged from 0.44% to 4.92% and from 0.90% to 33.95%, respectively." (PMID 41408046, 2025). "For example, TGFβ–BMP signalling was mostly inactivated by co-SMAD SMAD4 mutations in MSS cancers, but by one or more indel receptor mutations (TGFBR2, ACVR2A, BMPR2 and ACVR1B) in MSI cancers." (PMID 39112709, 2024). "Key biological concepts extracted from a series of PubMed queries established indirect links between ACVR1B and “cancer”, “TGF-beta superfamily”, “cell proliferation”, “inhibitors of activin”, and “apoptosis”." (PMID 37020544, 2023). "TUG1 regulated the cancer genes ACVR1B and BCL2 in KIRC, while it competitively regulated PPARG in BLCA." (PMID 27580177, 2016). "According to the immunostaining results, the expressions of p21 were clearly elevated in the cancer cells of patients with wild-type ACVR1B and SMAD4 genes, compared with the expression levels in patients with the homozygous deletion of the ACVR1B gene." (PMID 24886203, 2014). "We initially assessed alterations in the ACVR1B gene in human cancer patient cohorts." (PMID 41408046, 2025). "We identified a homozygous deletion of the ACVR1B gene in PC cell lines and clinical samples and proposed that the deletion of the ACVR1B gene may mediate an aggressive cancer phenotype in PC." (PMID 24886203, 2014). "The downexpression of these miRNAs significantly reduced cancer cell proliferation and apoptosis by targeting FOXO-3, CLSPN, ACVR1B, E2F4 and PPP2CA and regulated cell cycle progression by targeting CDKN2A and FOXO-3." (PMID 34743742, 2021). "The implication of ACVR1B and BMP in cancer has exhibited a dual function according to different cancer cell types or different BMP ligands, promoting or preventing critical cancer hallmarks such as stemness, migration, or proliferation." (PMID 33066614, 2020). "The combined 208 cases yielded no additional high-frequency mutated genes, however, multiple lower frequency (<2.5% recurrence) cancer-related genes were identified including ATM, ARID2, TGFBR2 and ACVR1B." (PMID 25855536, 2015). "Some up-regulated genes such as ACVR1B, FYN and CTTN, and some down-regulated genes such as PTEN, are known to be correlated with cell migration and cancer metastasis." (PMID 21998723, 2011). "Fifty of fusion genes have been reported and 14 involving known cancer genes (ALDH2-ACAD10, BIRC6-SPAST, BIRC6-TTC27, CGNL1-TCF12, CPEB3-IDE, CTNNA1-KDM3B, DNAJB1-PRKACA, LRP5-CHKA, PPFIBP1-STK38L, RNF213-SLC26A11, RXRA-WDR5, SEC16A-NOTCH1, WNK1-ERC1, and ACVR1B-ACVRL1)." (PMID 37403120, 2023).
infection (5 papers, 2014 to 2023). The state of being infected such as from the introduction of a foreign agent such as serum, vaccine, antigenic substance or organism. "In primary infection, the SMAD protein Smad2 was found to interact with Acvr1b; whereas in secondary infection, Smad2, Smad3, and Smad7 were found to interacted with Acvr1b." (PMID 25341656, 2014). "To clarify the role of TGF-β in the innate and adaptive immune response, we focused on the protein interactions of SMAD proteins and Acvr1b in primary and secondary infection, and compared the differences between initial and recurring infections." (PMID 25341656, 2014). "In summary, the identification of Acvr1b in primary and secondary infection suggests that TGF-β signaling is indeed involved in the control of innate and adaptive immune responses." (PMID 25341656, 2014). "Acvr1b, a type 1B activin receptor, has been shown to be related to the apoptotic process in both primary and secondary infection." (PMID 25341656, 2014). "Furthermore, the discovery that Smad7 interacted with Acvr1b only during secondary infection suggests that TGF-β controls immune responses via a SMAD-dependent pathway." (PMID 25341656, 2014). "Gene expression analysis showed that Smad2 is significantly down-regulated while Smad1 and the activin receptor gene Acvr1b are up-regulated in the resistant BALB/c mouse during infection, but not in the susceptible CBA/Ca." (PMID 24594938, 2014). "Acvr1b (ALK4, activin receptor type 1B) was identified to be a hub protein in both primary and secondary infection." (PMID 25341656, 2014). "However, Smad7, an I-SMAD, was found to interact with Acvr1b during secondary, but not primary, infection." (PMID 25341656, 2014). "Smad7 protein was found to interact with Acvr1b during secondary but not primary infection." (PMID 25341656, 2014).
bacterial infection (1 paper, 2018). "Our analysis revealed downregulation of miRNA-150 during bacterial infection may exert broad effects on metabolism (SLCA2A3/GLUT3), cytokine regulation (SOCS1), and cell signaling pathways (MAPK13, IPO8, ACVR1B, RNF146) consistent with the host response to bacterial infection." (PMID 30619110, 2018).
ACVR1B also shares sentences with these, for which no sentence is quoted: melanoma (4 papers); adenoma (2); cardiac hypertrophy (2); colon adenoma (2); endometriosis (2); myocardial infarction (2); ovarian carcinoma (2); sarcopenia (2); seminoma (2); triple-negative breast carcinoma (2); Ventricular arrhythmia (2); acute myocardial infarction (1); Alport syndrome (1); atrial fibrillation (1); bacteremia (1); basal cell carcinoma (1); cardiomyopathy (1); COVID-19 (1); cyst (1); diabetes (1); Duchenne muscular dystrophy (1); dystrophin deficiency (1); glioblastoma (1); gout (1); heart failure (1); Hypertension (1); influenza (1); ischemia (1); lipodystrophy (1); liver cirrhosis (1).
A further 18 diseases each share a sentence with ACVR1B in 1 paper.